STAT3 (signal transducer and activator of transcription 3)
Diseases named in the same sentence as STAT3 in open-access papers (continued):
Sharing a sentence is not in itself a finding about the gene and the disease.
colitis (continued). "The signal transducer and activator of transcription (STAT)-3 is an important transcription factor involved in the inflammatory pathogenesis of colitis." (PMID 32038241, 2019). "In an animal model, the deletion of Stat3 in hematopoietic cells led to spontaneous colitis, and intestinal epithelial cell-specific Stat3-deficient mice exhibited severe chronic inflammation." (PMID 31277507, 2019). "This was accompanied by a more pronounced inflammatory response during colitis and an elevated Stat3-dependent proliferation of IEC." (PMID 30353167, 2019). "Collectively, these results suggest that anti-colitis effects of EEP are caused by NF-κB and STAT3 inactivation both in vivo and in vitro." (PMID 30621304, 2019). "The activation of innate responses mediated by STAT3 signaling contributes to the amelioration of colitis." (PMID 31277507, 2019). "Thus, we hypothesis that RAI16 knockout could suppress the secretion of IL-18 and the expression of IL-22 binding protein (IL-22BP) in intestinal epithelial cells, consequently downregulate the secretion of STAT3-dependent Reg3γ and Reg3β, all together, which induces dysbiosis linked colitis." (PMID 31862898, 2019). "Activation of STAT3 in adaptive immune cells such as CD4+ T cells contributes for the development of colitis in a mouse model of CD." (PMID 29075900, 2018). "We now show that during the late phases of induced colitis, phosphorylation of STAT3 is present on nearly 20% of all cLP CD3+FoxP3−RORγt+ and CD3+FoxP3−RORγt− cells, while it is barely expressed in CD3+FoxP3+ RORγt− regulatory T cells." (PMID 30619314, 2018). "In this study, we identified TRIM27 as an important mediator of STAT3 activation, which also plays a role in colitis and CAC development." (PMID 30143645, 2018). "In colitis rats, the observed up-regulation of pro-inflammatory cytokines including IL-6 was ameliorated by CP, meanwhile, phosphorylation of Stat3 and JAK2 was blocked." (PMID 30042683, 2018). "Mutations in STAT3 have been identified as susceptibility factors for IBD and loss of epithelial STAT3 rendered mice more susceptible to DSS colitis." (PMID 30455690, 2018). "TLR4/NF-κB and IL-6/JAK2/STAT3 signal pathways were investigated to evaluate the alleviation of CP on the TNBS-induced colitis." (PMID 30042683, 2018). "Previously, we demonstrated that CST was associated with an activation of STAT3 and that CST protected against colitis." (PMID 30241336, 2018). "In a spontaneous model of murine colitis, the prevalence of B10 Bregs increases at the peak of inflammation and suppresses the disease by attenuating IL-1 and STAT3-mediated processes of immune reactivity." (PMID 29774025, 2018). "The authors further demonstrated via CHIP-seq analysis that STAT3 binds and promotes epigenetic remodeling of both Th17- and anti-apoptotic/survival-associated genes suggesting a complex role for T cell-intrinsic STAT3 in the progression of colitis." (PMID 29910812, 2018). "Intra-rectal administration of CST reduced the severity of experimental colitis, IL-18 colonic levels, maintained TJ proteins and enhanced the phosphorylation of STAT3." (PMID 30241336, 2018). "Used in this study as a positive control, Curcumin has been demonstrated to prevent colitis by suppressing NF-κB and inhibiting STAT3 signaling." (PMID 30289911, 2018). "Most importantly, these later studies demonstrated that blockade of IL-6 trans signaling suppressed T-cell resistance against apoptosis, which reduced intestinal inflammation, indicating that STAT3 activation in T cells contributes to colitis." (PMID 30081609, 2018). "Next, we analyzed Akt, STAT1 and STAT3 in colonic cell lysates of WT and Myo1F−/− animals that were induced to colitis." (PMID 30687322, 2018). "Studies have shown that activated STAT3 was found in human and animal colitis models, and over expression of STAT3 was always accompanied by more serious of the disease state." (PMID 30042683, 2018).
colitis (continued). "It was reported widely that NF-κB and STAT3 were two major transcriptional factors activated in colitis." (PMID 29724065, 2018). "The results showed that the protein levels of STAT3 and p-STAT3 were all enhanced in colitis comparing with the control group." (PMID 29724065, 2018). "Our results showed that the protective effect of TRYP on colitis was exerted through preventing NF-κB transfer to nucleus and the phosphorylation of STAT3." (PMID 29724065, 2018). "To investigate the cellular mechanisms of RA that are responsible for DSS-induced colitis, we examined the effect of RA on STAT3 activation in DSS-induced colon tissues." (PMID 28383063, 2017). "In summary, our study shows that RA significantly ameliorates systemic symptoms in a murine DSS-induced colitis model and suppresses expression of pro-inflammatory cytokines and inflammatory mediators through regulation of NF-κB and STAT3 activation." (PMID 28383063, 2017). "Th17 cells and STAT3-mediated inflammation correlate with autoimmune diseases like experimental autoimmune encephalitis and colitis." (PMID 29333002, 2017). "Clinical studies and animal experiments have demonstrated a crucial role of proinflammatory pathways, especially the NF-κB, IL-6/STAT3, COX-2/PGE2, and IL-23/Th17 signaling pathways, in the pathogenesis of colitis-associated CRC." (PMID 28852270, 2017). "Rosmarinic acid has recently been shown to suppresses DSS-induced colitis which is attributed to its dual inhibition of NF-κB and STAT3 activation." (PMID 28848431, 2017). "In this study, we demonstrated the inhibitory effect of RA on the constitutive activation and translocation to nucleus of NF-κB and STAT3 Tyr705 in mice with DSS-induced colitis." (PMID 28383063, 2017). "STAT3 inhibition was reported recently to attenuate DSS induced colitis development by suppressing IL-17 production." (PMID 27258062, 2016). "In the model of mice colitis, we also found that p-STAT3 and AChE increased expressed in intestinal CD68-positive cells in DSS mice compared with sham ones." (PMID 27977009, 2016). "Compared with control group, the phosphorylation level of STAT3 was increased in DSS-induced colitis mice." (PMID 27574508, 2016). "Throughout the multistep process of tumorigenesis in colitis-associated CRC, inflammatory cytokines drive activation of key pro-tumorigenic transcription factors (e.g. NF-κB and STAT3) in IECs to promote tumor cell proliferation and resistance to apoptosis." (PMID 27344176, 2016). "We found that sodium propionate inhibited phosphorylation of STAT3 induced by colitis, which is consistent with the previous report that multi-fiber mix feeding decreased p-STAT3 expression in colonic mucosa of IL-10-/- mice." (PMID 27574508, 2016). "Such mice displayed severer experimental colitis, reduced phospho-STAT3 levels and decreased proliferation of IECs." (PMID 26938566, 2016). "The IL6/STAT3 pathway activation has been shown to play a role in colitis by promoting inappropriate survival of T cells." (PMID 27525335, 2016). "In concrete terms, IL-22 has been shown to induce epithelial STAT3 activation and reduce disease activity of experimental colitis in mice via recovery of goblet cells and restoring the mucus layer." (PMID 26938566, 2016). "In children with UC and mice with experimental colitis, miR-124 levels were significantly decreased while STAT3 and downstream genes were up-regulated." (PMID 27525335, 2016). "As the mesenteric lymph node is important in DSS induced colitis progression, we determined Grim19, STAT3 and IL-17 expression in the mesenteric lymph nodes of mice with DSS induced colitis." (PMID 27258062, 2016). "There are several evidences that STAT3 deletion can induce severe colitis progress and DSS-induced intestinal injury." (PMID 27258062, 2016).
colitis (continued). "It has been suggested that haplotype complied by risk alleles of STAT3 polymorphism is significantly related to Crohn’s disease and ulcerative colitis, clinical phenotypes of DSS induced colitis." (PMID 27258062, 2016). "Transgenic mice overexpressing Grim19 exhibited improvement of DSS induced colitis progression due to downregulation of p-STAT3 and proinflammatory cytokines in the colon." (PMID 27258062, 2016). "Nevertheless, by inducing chronic inflammation as well as STAT3 and NFκB activation, IEC-specific deletion of Shp-2 results in the formation and growth of pre-malignant and malignant lesions typical of colitis-associated carcinogenesis." (PMID 27582544, 2016). "Consistent with previous reports, Iκb and STAT3 were phosphorylated during colitis, indicating development of inflammation." (PMID 25915426, 2015). "We observed that STAT3 expression was upregulated in the colon of DSS-mediated colitis, which is consistent with previous reports." (PMID 25973440, 2015). "Transgenic mice deficient for STAT3 in their hematopoietic system can develop a lethal form of colitis as result of chronic gut inflammation, demonstrating the importance of STAT3 in sequestering immune cell activation." (PMID 24806510, 2014). "Here we demonstrate that loss of SK1 from either source results in decreased STAT3 phosphorylation upon acute DSS treatment, indicating the importance of SK1 for STAT3 activation in short term models of colitis as well." (PMID 25460165, 2014). "To explore the effects of heat-killed VSL#3 on regular intestinal mucosal internal environment, we observed the level of the expression of IL-6/STAT3 trans-signaling related cytokines in large intestine from rats with colitis induced by dextran sulfate sodium." (PMID 24451125, 2013). "In a mouse model of AOM/DSS-induced colitis-associated CRC, deletion of STAT3 in enterocytes resulted in reduced tumor load in the intestine." (PMID 23940556, 2013). "It has been previously demonstrated that specific ablation of STAT3 in intestinal epithelial cells suppresses cell proliferation and reduces tumor incidence in both a DSS-induced colitis model and colitis associated cancer (CAC) model." (PMID 23379788, 2013). "STAT3 deletion in macrophages and neutrophils produces chronic enterocolitis, while STAT3 expression in T cells is essential for the induction of colitis." (PMID 22675454, 2012). "In mammals, the JAK/STAT pathway is a key signaling mechanism for growth factors and cytokines, and activation of STAT3, in particular, protects against the development of colitis and promotes intestinal repair following mucosal injury." (PMID 22675454, 2012). "For example, STAT3 activation in intestinal epithelial cells protects against the development of colitis and enhances intestinal restitution, findings consistent with our observations." (PMID 22675454, 2012). "In aggregate, these studies highlight a cell-type specific role of STAT3 in the regulation of mucosal healing following colitis." (PMID 22675454, 2012). "STAT3 activation in murine colitis is dependent on IL-22, which is secreted by cells of the innate immune system." (PMID 22675454, 2012). "We demonstrated a novel mechanism in which IL-6 increases S100A9 levels via STAT3 activation in CECs in an experimental murine model of DSS-induced colitis." (PMID 22962574, 2012). "By contrast, the very mechanisms that confer resistance to colitis in Stat3 proficient epithelium also promote tumourigenesis, including IL22-dependent induction of tumour-promoting inducible nitric-oxide synthase." (PMID 20478049, 2010). "Importantly, disruption of this modification through K709-specific inhibition effectively blocks STAT3 activation and, consequently, exacerbates colitis progression." (PMID 42220092, 2026). "Additionally, SIRT1, a key player in cellular metabolism and stress response, interacts with the STAT3 signaling cascade, thereby modulating the inflammatory response in colitis." (PMID 40672369, 2025).
colitis (continued). "Additionally, it is recognized as a potential inducer that leads to tumorigenesis from colitis through the IL-6/STAT3 (signal transducer and activator of transcription 3)/NF-κB (nuclear factor κB) signaling pathway." (PMID 40565156, 2025). "In murine models, STAT3 deficiency (Stat3ΔIEC) leads to delayed wound healing, increased tissue damage, reduced epithelial proliferation, and heightened apoptosis in DSS-induced colitis." (PMID 39860613, 2025). "Investigating the SIRT1/STAT3 axis in colitis may provide critical insights for developing novel IBD therapies." (PMID 40672369, 2025). "To verify whether B. velezensis MZ09 alleviates colitis in piglets through GPR43-mediated STAT3 expression, we detected STAT3 phosphorylation levels." (PMID 40883849, 2025). "Both our in vivo and in vitro experiments demonstrated that SPS may alleviate colitis inflammation and modulate the intestinal immune system through the STAT3/NF-κB signaling pathway." (PMID 41008172, 2025). "Our study contributes valuable insights into the potential therapeutic applications of herbal-based therapies for chronic inflammatory conditions, emphasizing the role of PPPG in modulating the IL-6/STAT3 pathway and demonstrating its efficacy in a preclinical model of colitis." (PMID 40733052, 2025). "In colitis, multiple proinflammatory cytokines within the intestinal tissue abnormally activate STAT3, resulting in intestinal barrier dysfunction, hyperactivation of innate immunity, and enhanced Th17-mediated immune responses, all of which contribute to chronic intestinal inflammation." (PMID 40672369, 2025). "Our investigation has indicated that dietary LCFAs can enter intestinal epithelial cells via CD36-mediated uptake and endocytosis, thereby participating in the palmitoylation cycle of STAT3 and exacerbating colonic inflammation, which plays a notable role in the development of UC." (PMID 38233383, 2024). "We also detected oxidative stress-related biomarkers, inflammatory cytokines, and potential nuclear factor erythroid 2-related factor 2 (Nrf2)/heme oxygenase 1 (HO-1) and janus kinase 2 (JAK2)/signal transducer and activator of transcription 3 (STAT3) pathways in the colitis tissues." (PMID 39133435, 2024). "Similarly, B. pseudolongum supplementation was also found to be able to attenuate colitis by increasing the intestinal proportion of Foxp3+T cells and modulating the Pparγ/STAT3 pathway in DSS-fed mice." (PMID 39275234, 2024). "Thus, we conclude that RelA and Stat3-driven accumulation of CDCA aggravates intestinal inflammation-induced damage during experimental colitis." (PMID 39137024, 2024). "At the molecular level, RA could suppress proinflammatory cytokines and inflammatory mediators by inhibiting the NF-kB/STAT3 signaling pathway, which has been confirmed by the use of commercial RA in colitis mice." (PMID 38731431, 2024). "Interestingly, nuclear actin polymerization is highly related with expression of PIAS3, which modulates signal transducer and activator of transcription 3 and NF-κB activity in colitis." (PMID 39183944, 2024). "Initiation of colitis in mice leads to hepatic Rela and Stat3 activation." (PMID 39137024, 2024). "Notably, the current study revealed that ART1 knockdown significantly reduced p-STAT3 expression in transplanted tumours in a DSS-induced colitis mouse model." (PMID 38504172, 2024). "DSS-induced colitis model animals have been reported to have elevated levels of several proinflammatory cytokines, including IL-6 and IL-11, both of which are associated with CRC development via p-STAT3." (PMID 38504172, 2024). "JAK2 and STAT3 constituted a membrane-to-nucleus signaling module, the phosphorylation of which participates in the expression and biological effect of various inflammatory mediators in colitis." (PMID 38397811, 2024).
colitis (continued). "The mechanisms through which CSCC protects against DSS-induced colitis may include upregulating Gpr43, inhibiting the STAT3/NLRP3 pathway, and suppressing inflammation factors like IL-17A." (PMID 39329121, 2024). "Our western blot analysis revealed that XYKJP significantly suppressed JAK2 and STAT3 phosphorylation, suggesting that XYKJP's potential therapeutic effects on colitis may be mediated through the inhibition of the JAK2/STAT3 pathway." (PMID 39133435, 2024). "Overall, XJS might alleviate experimental colitis via suppression of the FGL1/NF-κB/STAT3 positive feedback loop." (PMID 37153794, 2023). "Pharmacological inhibition of the MALT1 protease during recovery from experimental colitis significantly reduced Stat3 expression levels as well as STAT3 activation in the intestinal epithelium, which in turn might have promoted the delay in mucosal healing." (PMID 37108564, 2023). "Likewise, upregulation of p-STAT3 was significantly impaired in colonic IECs from Gpr65ΔIEC mice after induction of DSS colitis." (PMID 37749885, 2023). "Accumulated studies have demonstrated that RosA possesses immunomodulatory effects for alleviating chronic or acute inflammation diseases (such as arthritis, colitis, asthma and lung injury) through acting on multiple molecular targets, including NF-kB, p-STAT3, and MAPKs." (PMID 37891648, 2023). "In addition to being implicated in colitis, CD4+Th17 cells have been shown to depend on STAT3 for their normal development." (PMID 37296943, 2023). "Inhibition of overexpressed NF-κB and STAT3 can effectively alleviate experimental colitis." (PMID 37153794, 2023). "Importantly, we determined that a selective, small-molecule inhibitor of STAT3, TTI-101, completely prevented DSS-induced colitis as well as the upregulation of CRC-associated genes." (PMID 37296943, 2023). "In an AOM/DSS-induced colitis associated CRC model in BALB/c mice, fisetin suppressed dysplastic lesions through inducing apoptosis in the colonic tissue along with downregulation of Bcl-2 and STAT3, and upregulation of cleaved-caspase-3 and BAX." (PMID 36765950, 2023). "However, other results indicate STAT3 deletion in myeloid cells also leads to exacerbation of colitis." (PMID 37283760, 2023). "The protective effects of IL-22 in colitis were dependent on epithelial STAT3 activation." (PMID 37432218, 2023). "We also found increased expression of IL-6 and STAT3 signaling in Cldn3KO mice with colitis." (PMID 38010872, 2023). "Moreover, a T cell-specific STAT3 deletion has been reported to ameliorate dextran sulfate sodium-induced colitis in mice by reducing the inflammatory response." (PMID 37170220, 2023). "To verify the assumption, we administered B. fragilis to mice in a DSS-induced colitis mouse model and found that B. fragilis facilitates colonic mucosa proliferation, and mucus secretion, and alters gut microbiota in colitis via motivating the STAT3 pathway induced by IL-22 from ILC3 secretion." (PMID 37114045, 2023). "Inactivation of STAT3 in intestinal epithelium affects cell survival proliferation in colitis." (PMID 38002302, 2023). "In conclusion, XJS might restrain ferroptosis in IECs to ameliorate experimental colitis by inhibition of FGL1/NF-κB/STAT3 positive feedback loop." (PMID 37153794, 2023). "We demonstrated that DSS-induced colitis is more severe in mice that express only STAT3α compared to wild-type mice and that administration of a selective, small-molecule inhibitor of STAT3, TTI-101, completely prevented DSS-induced colitis as well as reversed upregulation of CRC-associated genes." (PMID 37296943, 2023). "B. fragilis may indirectly motivate ILC3 to secrete IL-22, followed by IL-22-induced STAT3 phosphorylation, hence promoting colonic mucosa regeneration in colitis." (PMID 37114045, 2023).